CDK2 (cyclin dependent kinase 2)
Diseases named in the same sentence as CDK2 in open-access papers (continued):
Sharing a sentence is not in itself a finding about the gene and the disease.
breast cancer (continued). "Taken together, these findings demonstrate a novel positive feed-back loop between cyclin-A/Cdk2 and Aurora-A pathways in the development of centrosome amplification in breast cancer cells." (PMID 23446853, 2013). "Taken together, these findings demonstrate at the mechanistic level a novel interplay between cyclin-A/Cdk2 and Aurora-A oncogenic signalings in the development of centrosome amplification in breast cancer cells." (PMID 23446853, 2013). "In conclusion, these findings highlight a novel positive feedback loop between cyclin-A/Cdk2 and Aurora-A pathways in the development of centrosome amplification in breast cancer cells." (PMID 23446853, 2013). "Due to extensive evidence that Cdk2 and Cdk4 are important genetic links between CA, mitotic errors, and transformation, we explored their role as major regulators of CA in Her2+ breast cancer cells." (PMID 23776583, 2013). "Understanding the requirements of human breast epithelial cell transformation and the unique role of constitutive CCND1/CDK2 activity can guide the development of targeted strategies to treat breast cancer." (PMID 23390492, 2013). "Our results demonstrated that induction of genotoxic stress induces centrosome amplification through stabilization and activation of Aurora-A kinase mediated by Cdk2 oncogenic signaling in breast cancer cells." (PMID 23446853, 2013). "Constitutive CCND1/CDK2 activity conferred resistance to TGF-β induced growth arrest in MMTVD1-K2 driven mouse mammary tumor cells, and CCND1 is a downstream effector of RAS." (PMID 23390492, 2013). "Accumulation or over-expression of cyclin D1 (CCND1) occurs in a majority of breast cancers and over-expression of CCND1 leads to accumulation of activated CCND1/CDK2 complexes in breast cancer cells." (PMID 23390492, 2013). "Consistent with our finding, previous studies showed that the addition of exogenous cyclin EL increases the formation of cyclin EL/CDK2 complex correlating to the increased activity and phosphorylation of CDK2 in human lung fibroblasts and breast cancer cells." (PMID 23437375, 2013). "In human breast cancer, the mechanistic relationship between deregulated activity of the cyclin-A/Cdk2 complex and Aurora-A kinase in the induction of centrosome amplification has not been investigated." (PMID 23446853, 2013). "In the present study, we investigated the mechanistic linkage between cyclin-A/Cdk2 and Aurora-A oncogenic signalings in the development of centrosome amplification in human breast cancer cell models." (PMID 23446853, 2013). "Somatic alterations of cyclin-dependent kinase 2 (CDK2)-cyclin E complex have been shown to contribute to breast cancer (BC) development and progression." (PMID 23185313, 2012). "The observation that cancer cells harbouring CCNE1 gene amplification are sensitive to CDK2 inhibitors provides a rationale for the testing of these chemical inhibitors in a subgroup of patients with ER-negative grade III breast cancers." (PMID 22433433, 2012). "The enzymatic activity of the cyclin-dependent kinases 1 and 2 (CDK1 and CDK2) predicts outcome in breast cancer." (PMID 22108518, 2012). "This decrease in Cdk2 mRNA by the Cdk2i scaffold translated to a ∼40% decrease in the proliferation of the breast cancer cell line, MCF-7, as well as the presence of increased number of dead cells." (PMID 23285007, 2012). "For example, MAPK and CDK2 or CDK4/6 are known drivers of breast cancer progression that likely induce persistent PR Ser294 phosphorylation in some breast tumors." (PMID 22697792, 2012).
breast cancer (continued). "Cyclin E, an activator of CDK2, when ectopically over-expressed is able to abrogate the anti-proliferative actions of tamoxifen on breast cancer cells and is also shown to be a good indicator for endocrine-therapy failure." (PMID 21834972, 2011). "In this study, we show that roscovitine, a potent inhibitor of CDK2, can curb the growth of therapy-resistant breast cancer cells and to down regulate expression of ERα." (PMID 21834972, 2011). "Earlier studies that showed functional ablation of retinoblastoma protein (pRb) leads to activation of CDK2 in breast cancer and concordantly, that deregulation of E2F transcription factor target genes associated with poor prognosis." (PMID 21834972, 2011). "We measured the specific activities of CDK1 and CDK2 in the four breast cancer cell lines after treatment with 100 nM paclitaxel." (PMID 19239702, 2009). "We then examined the specific activities of CDK1 and CDK2 in these cell lines and in xenograft models of human breast cancer before and after paclitaxel treatment." (PMID 19239702, 2009). "In the present study we measured both the kinase activity and expression level of CDK1 and CDK2 before and after paclitaxel treatment in human breast cancer cell lines and in xenograft models of human breast cancer." (PMID 19239702, 2009). "In summary, these results support a model in which the mitogenic effects of estrogen in breast cancer cells are largely mediated by inactivation of pRb and/or related family members, which in turn leads to cdk2 activation and cell cycle progression." (PMID 18060053, 2007). "Estrogen treatment leads to the activation of both cdk2 and cdk4 in breast cancer cell lines, and both of these kinases can phosphorylate pRb." (PMID 18060053, 2007). "These inhibitors of cdk2 that are in clinical trials are potential therapies for antiestrogen resistant breast cancers with alterations in the pRb pathway." (PMID 18060053, 2007). "Also, hyperglycemia was reported to increase the proliferation of breast cancer cells by upregulating cdk2 (cyclin dependent kinase 2) and cyclin D1, which in-turn accelerate the cell cycle progression." (PMID 40735043, 2025). "Apart from CDK4/6, CDK2 is also involved in cell cycle progression through the G1, S, and G2 phases, and aberrant CDK2 activation is associated with CDK4/6 inhibitors in HER2-responsive breast cancers." (PMID 41463161, 2025). "HBV infection may lead to increased expression levels of several key genes in breast cancer cell lines, including CDK2, PCNA, CCNE2, CXCL8, E2F1, and CASP3." (PMID 40697521, 2025). "Additionally, resistance to CDK4/6 inhibitors in breast cancer is acquired through CDK2-mediated phosphorylation of c-MYC, which enables cells to escape senescence." (PMID 40904502, 2025). "In vivo cell experiment, we confirmed that HBV infection may lead to increased expression levels of several key genes in breast cancer cell lines, including CDK2, PCNA, CCNE2, CXCL8, E2F1, and CASP3." (PMID 40697521, 2025). "The cyclin E:CDK2 complex has been reported to be involved in breast cancer progression." (PMID 39604563, 2025). "In tumor cells such as those of breast cancer and lung cancer, CDK2 is often hyperactivated." (PMID 39999107, 2025). "Additionally, molecular docking studies indicated favorable interactions of 5f with CDK2 and Bcl─2 proteins, supporting its potential role in breast cancer treatment." (PMID 40911852, 2025). "We investigated the significance of CDK2 in breast cancer utilising CBioportal." (PMID 38732271, 2024). "A key issue relevant to the clinical development of CDK2 inhibitors in luminal breast cancer is whether they might not only overcome acquired resistance to CDK4/6 inhibition, but also prevent it." (PMID 38047585, 2024). "We provide compelling evidence that high CDK2 is a feature of aggressive breast cancers." (PMID 38732271, 2024).
breast cancer (continued). "Advanced scRNA-seq and spatial molecular profiling in tumor specimens supported EGFR expression and higher expression of CDK2/cyclin E in TNBC compared with other breast cancer types across primary and post-NAC-resistant TNBCs, and higher levels of co-expression and spatial colocalization in TNBCs." (PMID 38772416, 2024). "Dinaciclib that inhibits the CDK2 is currently in clinical trials for breast cancer." (PMID 37925393, 2023). "In addition, inhibitors of CDK7, a cyclin-activating kinase, CDK2 and CDK2/4/6 inhibitors are in clinical development in ER+ breast cancer." (PMID 37921419, 2023). "The drug response test using PDOs further validated that high MITH was an indicator for CDK4/6 inhibitor resistance in HR+ breast cancers and CDK2/4/6 inhibitor may be an effective option for the patients with high-MITH HR+ breast cancer." (PMID 37880211, 2023). "In breast cancer cells, concurrent administartion of CDK2 and CDK4/6 inhibitiors could reverse palbociclib resistance through increasing cell senescence." (PMID 36266723, 2022). "Our results suggested that miR-885-3p could suppress the proliferation of breast cancer cells, partially by suppressing the expression levels of CDK2/CCNE1 and CDK4/6/CCND1 and arresting the cell cycle in the G0/G1 phase." (PMID 35383130, 2022). "Taken together, these data suggest a mechanism of action in which inhibition of ATR in intact RNF126 cells induces an increase in CDK2-mediated replication stress in breast cancer cells, ultimately leading to DNA damage, replication fork collapse, cell apoptosis, and cell death." (PMID 36539893, 2022). "CDK2 may mediate the killing effect of ATR inhibitors on RNF126 high-expression breast cancer cells." (PMID 36539893, 2022). "As a star molecule, CDK2 participates in classic pathways in various cancers, such as colorectal cancer, neuroblastoma, breast cancer, hepatocellular carcinoma, and prostate cancer." (PMID 34409029, 2021). "It was suggested that inhibition of breast cancer cell MCF-7 proliferation may be linked to the upregulation of cyclin E and p21 as well as downregulation of CDK2 upon NC extract treatment." (PMID 34721030, 2021). "CDK7, a transcriptional CDK exhibiting CDK activating kinase activity on CDK2 and CDK9, has recently been found to be involved in the resistance mechanisms to CDK4/6i in CDK4/6i-resistant ER+/HER2− breast cancer cell models with loss of Rb and exhibiting cyclin E1 overexpression." (PMID 34771560, 2021). "Indeed, a kinome-wide siRNA screen analysis showed that overexpression of PDK1 resulted in the activation of AKT and CDK2 in ribociclib-resistant breast cancer cell models." (PMID 34771560, 2021). "CDK2 is a target for retinoic acid-mediated growth inhibition in MCF-7 human breast cancer cells." (PMID 34444715, 2021). "Based on the structural analysis of previously reported CDK2 inhibitors, a new compound with 3-hydrazonoindolin-2-one scaffold (HI 5) was well designed, synthesized, and biologically evaluated as a promising anti-breast cancer hit compound." (PMID 33466812, 2021). "In addition, expression profiles of CDK2 and CDK4 were associated with tumor metastasis and breast cancer subtypes, with higher expression levels in basal and Her2 subtypes than the other subtypes." (PMID 34421361, 2021). "In summary, we have found that CDK2 inhibition may sensitize BRCA1 mutant breast cancer cells to PARP inhibitors." (PMID 34465787, 2021). "Moreover, we found that our novel tetracyclic derivative, BC-N102 suppressed tumorigenesis via inhibition of ER/Akt/PI3K/ERK/CDK2/4, and induced time-course G0/G1 cell cycle arrest of human breast cancer cells." (PMID 34421361, 2021).
breast cancer (continued). "ASOs targeting MAFG-AS1 and CDK2 inhibitors may provide a promising approach to inhibit luminal breast cancer progression and tamoxifen resistance." (PMID 33098638, 2020). "Therefore, the development of a CDK2-specific kinase inhibitor is a rational approach for the treatment of breast cancers that are resistant to CDK4/6 inhibitor." (PMID 33260316, 2020). "In addition, it was previously reported that PI3K/AKT/mTOR signaling pathway activation promotes cell cycle progression in CDK4/6 inhibitor resistant breast cancer cells through increased CDK2 and cyclin E." (PMID 32899250, 2020). "Our findings could pave the way for the development CDK2-specific kinase inhibitor for the treatment of breast cancers that are resistant to CDK4/6 inhibitor." (PMID 33260316, 2020). "Taken together, these data suggest that CDK1 and CDK2 may serve as potential biomarkers for predicting the outcome of cancer patients, especially those with breast cancer." (PMID 31428132, 2019). "Overall, these changes implicate CDK2 activity as an independent driving feature of BLBC, and this is strengthened by the observation that mouse mammary tumors that develop from mouse mammary tumor virus with constitutive Cdk2 expression, have basal-like features." (PMID 30720718, 2019). "Moreover, CDK2 was reported to promote cell viability and tumor progression in many other human cancers, including breast cancer 24, 25, colorectal cancer 26, squamous cell carcinoma of the head and neck 27, neuroblastoma 28 and nonsmall cell lung cancer." (PMID 29744291, 2018). "Our study reveals that RHBDD1 promotes breast cancer progression by regulating p-Akt and CDK2 protein levels, and might be a potential biomarker and prognostic indicator for breast cancer patients." (PMID 30286765, 2018). "Moreover, the protein level of RHBDD1, p-Akt and CDK2 was significantly positively correlated in breast cancer tissue." (PMID 30286765, 2018). "Treatment with CDK1/2 inhibitors or depletion of CDK2 efficiently inhibit growth and/or induce apoptosis in triple negative/basal breast cancer, MYCN-amplified neuroblastoma and myeloid leukemia cell lines and in mouse models of MYC-driven lymphoma and liver cancer." (PMID 28665315, 2017). "On the basis of these results, we hypothesized that breast cancer cells overexpressing cyclin E (including LMW-E) may be sensitive to CDK2 inhibitors either alone or in combination with other agents." (PMID 28107181, 2017). "Inhibition of CDK2 was shown to decrease breast cancer oncogenesis." (PMID 29137393, 2017). "Interestingly, in mouse models the kinase activities of some cyclin/CDK complexes, such as CDK4 and CDK2, appear dispensable for normal mouse development, but are required for mammary tumor development." (PMID 25914884, 2015). "High levels of Cyclin E in the nucleus have been reported to occur at an early stage in development of breast cancer, and low molecular weight forms of cyclin E are thought to be responsible for hyperactivation of CDK2 in breast cancer, melanoma and ovarian carcinoma." (PMID 25625291, 2015). "Inhibition of CDK2 activity could effectively restrain the proliferation of breast cancer cells, including those resistant to endocrinotherapy." (PMID 25550687, 2014). "Given the relationship between MYC dependence and CDK2 activity, we therefore assessed whether targeting CDK2 could block the proliferation of three MYC-dependent breast cancer cell lines." (PMID 24444383, 2014). "Expression of CDK2-AP1, CDK2 and CyclinD1 in 40 cases of normal breast tissues, 30 cases of ductal breast cancer in situ, 121 cases of invasive breast cancer and 18 cases of relapsed breast cancer were examined by immunohistochemical staining." (PMID 25550687, 2014).
breast cancer (continued). "The zinc finger-homeodomain transcription factor, δ-crystallin enhancer factor 1 (δEF1) has been identified as a regulatory factor involved in the promotion of breast cancer cell proliferation via the downregulation of p21 and the upregulation of cyclin-dependent kinase-2 (CDK2) and CDK4 expression." (PMID 24348783, 2014). "Interestingly, cAMP inhibits proliferation of breast cancer cells via increased expression of p27Kip1 and decreased activity of Cdk2." (PMID 24884804, 2014). "Because ablation of Cdk2 or Cdk4 suppresses Her2-driven mammary tumors and signals CA, the two Cdks may represent important links between CA and tumorigenesis." (PMID 23776583, 2013). "Taken together, these data suggest that targeted inhibition of constitutive CCND1/CDK2 activity may enhance the effectiveness of current treatments for luminal breast cancer." (PMID 23390492, 2013). "In addition to CCND1/CDK4 complexes, over-expression of CCND1 also leads to accumulation of activated CCND1/CDK2 complexes in breast cancer cells." (PMID 23390492, 2013). "Overexpression of CDK2 and CDK4 was associated with breast cancer progression." (PMID 22616919, 2012). "Given the crucial role of CDK2 in centriole amplification and the high frequency of its deregulation in early stage breast cancer, we asked here whether targeting CDK2 can prevent centrosome aberrations in breast cancer cells." (PMID 20565777, 2010). "Such transcriptional and post-transcriptional repression was observed in different NSCLC, prostate and breast cancer cell lines and we propose that this potentiates and synergizes the Roscovitine-mediated CDK2 inhibition thus resulting in a significant decrease of cellular NHEJ ability." (PMID 20684776, 2010). "In sensitive breast cancer lines, the reduction in cyclin D1 led to release of sequestered CDK inhibitors, p27Kip1 and p21Cip1, and association of these inhibitors with cyclin E/CDK2 complexes." (PMID 19046439, 2008). "Patients with such a primary breast cancer may therefore, benefit from other treatments, for instance from chemotherapy or potential cdk2 inhibitors." (PMID 11875707, 2002). "In addition, CDK-2 affects hormone-dependent cancers by phosphorylating the receptors of androgen, estrogen, and progesterone and increasing their transcriptional activity and CDK-2 inhibition has been reported to prevent the progression of prostate cancer and breast cancer." (PMID 38184514, 2024). "Thus, circ_6014 could influence breast cancer cellular proliferation via regulation of the cell cycle through changes in CDK2/CCNE1 and CDK4/6/CCND1 cell cycle proteins and regulation of the G0/G1 phase of the cell cycle." (PMID 35383130, 2022). "Furthermore, various cancer types showed dysregulations in CDK2 and/or its cyclin cognates such as breast cancer, endometrial, ovarian, thyroid, lung, hepatocellular carcinomas, melanoma, lymphoma, osteosarcoma, prostate, colorectal, pancreatic cancers, neuroblastoma, and BRCA deficient cancers." (PMID 35470754, 2022). "Thus, CDK2-mediated replication stress in breast cancer with a high level of RNF126 expression might be one of the reasons for the sensitivity of these breast cancer cells to ATR inhibitors." (PMID 36539893, 2022). "Moreover, early adaptation of ER+ breast cancer cell models to CDK4/6i has been associated with increased activity of CDK2 by noncanonical binding with cyclin D1 mediating G1/S transition cell cycle entry." (PMID 34771560, 2021). "In particular, glioblastoma, breast cancer, colon cancer, melanoma, lung adenocarcinoma, head and neck cancer, pancreatic cancer, liver cancer, and prostate cancer cohorts showed the most significantly (p < 0.001) elevated CDK2, CDK4, CDK6, and STAT3 expressions." (PMID 33668805, 2021). "MAFG-AS1 and CDK2 may become attractive therapeutic targets in ER+ breast cancer." (PMID 33098638, 2020). "Similarly, qRT-PCR data showed that CDK2 was up-regulated in 50 paired breast cancer tissues." (PMID 33098638, 2020).